ATP12A (ATPase H+/K+ transporting non-gastric alpha2 subunit)
Description:
The catalytic subunit of a H(+)/K(+) ATPase and/or Na(+)/K(+) ATPase pump which transports K(+) ions in exchange for Na(+) and/or H(+) ions across the apical membrane of epithelial cells. Uses ATP as an energy source to pump K(+) ions into the cell while transporting Na(+) and/or H(+) ions to the extracellular compartment. Involved in the maintenance of electrolyte homeostasis through K(+) ion absorption in kidney and colon (By similarity). In the airway epithelium, may play a primary role in mucus acidification regulating its viscosity and clearance.
Synonyms: ATP1AL1; HK; H-K-ATPase
Tractability: Small molecule: it belongs to a druggable protein family. Antibody: UniProt places it where antibodies can reach, with high confidence; its Gene Ontology location is reachable by antibodies, with high confidence; UniProt predicts a signal peptide or a membrane-spanning region. PROTAC: ubiquitination databases record sites on it; a small molecule that binds it is known.
Target class: P-type ATPase; Primary active transporter; Transporter; Hydrogen potassium ATPase
Gene: Protein-coding gene on chromosome 13 (24,680,408 to 24,712,472, forward strand). Ensembl gene ENSG00000075673.
Subcellular location: Apical cell membrane
Subcellular location (Human Protein Atlas): Actin filaments; Plasma membrane; Cytosol
Pathways (Reactome):
Transport of small molecules: Ion transport by P-type ATPases
Gene Ontology:
Molecular function: P-type potassium:proton transporter activity; P-type sodium:potassium-exchanging transporter activity; ATP binding; ATP hydrolysis activity; nucleotide binding; P-type potassium transmembrane transporter activity
Biological process: intracellular potassium ion homeostasis; intracellular sodium ion homeostasis; potassium ion import across plasma membrane; proton transmembrane transport; sodium ion export across plasma membrane; establishment or maintenance of transmembrane electrochemical gradient; potassium ion transport
Cellular component: apical plasma membrane; plasma membrane; potassium:proton exchanging ATPase complex; basolateral plasma membrane; cation-transporting ATPase complex; membrane; plasma membrane protein complex
Genetic constraint (gnomAD): Loss-of-function variants: 82 observed, 116.18 expected, observed/expected ratio (o/e) 0.71, 90% interval 0.59 to 0.85. The upper end of that interval is the gene's LOEUF score, 0.85, which puts it in group 3 of 6, group 1 being the genes least tolerant of losing a copy. Missense variants: 1,196 observed, 1,377.3 expected, observed/expected ratio (o/e) 0.87, 90% interval 0.83 to 0.91. Synonymous variants: 498 observed, 526.53 expected, observed/expected ratio (o/e) 0.95, 90% interval 0.88 to 1.02.
Homologues: Orthologues: chimpanzee ATP12A (99% identical), macaque ATP12A (96% identical), dog ATP12A (90% identical), guinea pig ATP12A (88% identical), pig ATP12A (87% identical), mouse Atp12a (87% identical), rat Atp12a (86% identical), rabbit ATP12A (85% identical), Caenorhabditis elegans catp-2 (37% identical), Caenorhabditis elegans catp-3 (36% identical), Drosophila melanogaster SPoCk (23% identical), Caenorhabditis elegans pmr-1 (23% identical), and 5 more. Paralogues in human: ATP4A (64% identical), ATP1A2 (64% identical), ATP1A1 (64% identical), ATP1A3 (63% identical), ATP1A4 (61% identical), ATP2B2 (28% identical), ATP2B1 (27% identical), ATP2B3 (27% identical), ATP2A1 (27% identical), ATP2A2 (27% identical), ATP2A3 (27% identical), ATP2B4 (27% identical), and 9 more.
Diseases named in the same sentence as ATP12A in open-access papers:
ATP12A is named in the same sentence as 71 diseases in open-access papers, as found by Europe PMC text mining. Sharing a sentence is not in itself a finding about the gene and the disease. The quoted sentences say what the papers report.
Hypertension (5 papers, 2011 to 2022). The presence of chronic increased pressure in the systemic arterial system. "Therefore, in the Flemish Study on Environment, Genes and Health Outcomes (FLEMENGHO) and the European Project On Genes in Hypertension (EPOGH) we investigated whether echocardiographic variables reflecting LV diastolic function are associated with common genetic variants in ATP12A." (PMID 25366262, 2014). "So far, only a whole DNA array survey in spontaneously hypertensive rats identified the ATP12A gene among probable candidate genes for hypertension." (PMID 25366262, 2014).
colorectal cancer (4 papers, 2018 to 2024). A primary or metastatic malignant neoplasm that affects the colon or rectum. "Similarly, potassium channels have been linked to tumorigenesis and increased expression of ATP12A (also known as ATP1AL1) has been associated with colorectal carcinomas." (PMID 35681710, 2022).
cystic fibrosis (4 papers, 2021 to 2026). Autosomal recessive disorder caused by pathogenic variants in the CFTR gene (cystic fibrosis transmembrane conductance regulator), which encodes a chloride and bicarbonate channel expressed in epithelial cells, and follow the diagnosis criteria. "Additionally, ATP12A, a H+/K+-ATPase localized at the apical membrane of airway epithelial cells, was shown to be a pathogenic factor in cystic fibrosis." (PMID 33808877, 2021). "Significantly downregulated genes in FOXI1-KO basal, secretory and ciliated cells included ATP12A, a proton pump involved in acidification of cystic fibrosis ASL16, and ATP1B1, an Na+/K+ ATPase." (PMID 37730992, 2023).
hypokalaemia (2 papers, 2021 to 2024). "On the other hand, HK-ATPase (Atp12a), which is stimulated by K+ depletion, is a positive K+-retaining adaptation to hypokalaemia." (PMID 34028587, 2021).
Meconium ileus (2 papers, 2019 to 2023). Obstruction of the intestine due to abnormally thick meconium. "Surprisingly, in addition to its relevance in CF airways, ATP12A has also been identified as a susceptibility locus for meconium ileus risk by the largest study population of individuals with CF from the international CF Gene Modifier Consortium (GMC)." (PMID 37892136, 2023). "Interestingly, meconium ileus risk was associated with increased ATP12A expression in the pancreas." (PMID 37892136, 2023). "With the eQTL findings pointing to the pancreas, the common allele variants in ATP12A that associated with meconium ileus risk are also associated with increased ATP12A expression, where even modest increases in proton secretion, may be critical in the absence of CFTR." (PMID 30807572, 2019). "Based on GTEx data, the meconium ileus risk alleles are associated with decreased SLC26A9 expression, but increased ATP12A and SLC6A14 expression in the pancreas." (PMID 30807572, 2019). "The associated modifier loci colocalized with expression quantitative trait loci (eQTLs) for ATP12A (p = 3.35x10-8), SLC6A14 (p = 1.12x10-10) and SLC26A9 (p = 4.48x10-5) in the pancreas, even though meconium ileus manifests in the intestine." (PMID 30807572, 2019).
Pancreatic Cancer (2 papers, 2020 to 2024). "ATP12A is overexpressed in human and murine pancreatic cancer." (PMID 38698303, 2024). "Here, we report that gastric and non-gastric H+, K+-ATPases (coded by ATP4A and ATP12A) are overexpressed in human and murine pancreatic cancer and that we can target them specifically with proton pump inhibitors (PPIs) and potassium-competitive acid blockers (P-CABs) in in vitro models of PDAC." (PMID 32164284, 2020).
chronic rhinosinusitis (1 paper, 2018). Chronic form of sinusitis. "Interestingly, the inhibitory effect of PPIs on ATP12A has been reported as a potential therapeutic approach in treating the inflammatory process in chronic rhinosinusitis." (PMID 30618754, 2018).
idiopathic pulmonary fibrosis (1 paper, 2023). Idiopathic pulmonary fibrosis (IPF) is a nonneoplastic pulmonary disease that is characterized by the formation of scar tissue within the lungs in the absence of any known cause. "Moreover, a recent study by Abdelgied and colleagues showed ATP12A upregulation in the distal small airways of idiopathic pulmonary fibrosis (IPF) and in submucosal glands and large airways of both IPF and COPD lung tissues collected from human donors." (PMID 37892136, 2023).
lung disease (1 paper, 2020). "Interestingly, ATP12A has been proposed as a modifier of lung disease severity via its role in pH regulation." (PMID 33090994, 2020).
prostate tumor (1 paper, 2022). "Of note, recent findings suggest an association in the expression pattern of ATP12A changing from membrane bound to cytosolic within the prostate tumor in contrast to healthy prostate tissue, which shows no overall increase in expression." (PMID 35681710, 2022).
pulmonary fibrosis (1 paper, 2023). Chronic progressive interstitial lung disorder characterized by the replacement of the lung tissue by connective tissue, leading to progressive dyspnea, respiratory failure, or right heart failure. "Abdelgied and colleagues, found that vonoprazan, like ouabain, increased the ASL pH of IPF small airway models and reduced bleomycin-induced pulmonary fibrosis in mice with ATP12A overexpression (produced by intratracheal instillation of adenovirus encoding ATP12A)." (PMID 37892136, 2023).
respiratory infection (1 paper, 2021). "Nonetheless, it was reported that without the innate proton pump ATP12A activity and airway acidification, CFTR-deficient mice are free from opportunistic Staphylococcus aureus respiratory infection, which makes airway acidification the deciding factor of murine opportunistic lung infections." (PMID 34867864, 2021).
cancer (10 papers, 2016 to 2024). A tumor composed of atypical neoplastic, often pleomorphic cells that invade other tissues. "For example, both KRT4 and ATP12A are among the top 10 genes identified by both indicators as factors of promoting cancer onset." (PMID 38459043, 2024).
adenocarcinoma (1 paper, 2025). A common cancer characterized by the presence of malignant glandular cells. "Other studies support our data showing mitochondrial energy metabolism gene expression varies between the metaplasia to adenocarcinoma disease sequence with some genes decreasing (ATP12A, COX4I2) and others increasing (COX8C)." (PMID 40381373, 2025).
bacterial infection (1 paper, 2022). "We found that IL-17/TNF-α, a stimulus that is associated with bacterial infection and neutrophilic infiltration, is particularly effective in enhancing ATP12A expression and function." (PMID 36219481, 2022).
cardiac disease (1 paper, 2020). "Atp12a, one of the upregulated genes, is of particular note due to its association with cardiac disease." (PMID 33287280, 2020).
inflammation (1 paper, 2023). Aberrant reaction of the microcirculation characterized by movement of fluid and leukocytes from the blood into extravascular tissues. "In this regard, Lennox and colleagues started dissecting the contribution of ATP12A to mucus dysfunction produced by IL-13, a key mediator of Type-2 airway inflammation." (PMID 37892136, 2023).
respiratory diseases (1 paper, 2022). "Based on the literatures, ATP12A is the nongastric form of H + /K + -ATPase and plays an important role in respiratory diseases." (PMID 35729678, 2022).
ATP12A also shares sentences with these, for which no sentence is quoted: tumor (6 papers); Dystonia (3); gastric ulcer (3); infection (3); atrophic gastritis (2); bipolar depression (2); brain ischemia (2); cardiac hypertrophy (2); diabetes (2); essential hypertension (2); gastritis (2); heart failure (2); Hypomagnesemia (2); ischemia (2); lung carcinoma (2); ulcer (2); amyotrophic lateral sclerosis (1); Areflexia (1); arteriosclerosis (1); atherosclerosis (1); autoimmune gastritis (1); breast carcinoma (1); cardiovascular disease (1); cataract (1); cerebellar ataxia (1); cholangiocarcinoma (1); cholera (1); Cognitive impairment (1); colon cancer (1); corneal edema (1).
A further 23 diseases each share a sentence with ATP12A in 1 paper.